CDT1 (chromatin licensing and DNA replication factor 1)
Description:
Required for both DNA replication and mitosis. DNA replication licensing factor, required for pre-replication complex assembly. Cooperates with CDC6 and the origin recognition complex (ORC) during G1 phase of the cell cycle to promote the loading of the mini-chromosome maintenance (MCM) complex onto DNA to generate pre-replication complexes (pre-RC). Required also for mitosis by promoting stable kinetochore-microtubule attachments. Potential oncogene (By similarity).
Synonyms: DUP; RIS2
Tractability: Small molecule: a structure with a bound ligand is known. PROTAC: UniProt records ubiquitination sites on it; ubiquitination databases record sites on it.
Gene: Protein-coding gene on chromosome 16 (88,803,789 to 88,809,258, forward strand). Ensembl gene ENSG00000167513.
Subcellular location: Nucleus; Chromosome, centromere, kinetochore
Subcellular location (Human Protein Atlas): Nucleoplasm; Nuclear bodies
Pathways (Reactome):
DNA Replication: Activation of the pre-replicative complex; Assembly of the pre-replicative complex; Orc1 removal from chromatin; Switching of origins to a post-replicative state
Cell Cycle: G1/S-Specific Transcription
Gene Ontology:
Molecular function: chromatin binding; protein binding; DNA binding
Biological process: attachment of mitotic spindle microtubules to kinetochore; DNA replication checkpoint signaling; mitotic DNA replication initiation; mitotic pre-replicative complex assembly; negative regulation of cell cycle; negative regulation of DNA-templated DNA replication; positive regulation of DNA replication; response to sorbitol; mitotic cell cycle; regulation of DNA-templated DNA replication initiation; DNA replication preinitiation complex assembly; regulation of DNA-templated DNA replication
Cellular component: kinetochore; nuclear body; nucleoplasm; nucleus
Genetic constraint (gnomAD): Loss-of-function variants: 64 observed, 45.26 expected, observed/expected ratio (o/e) 1.41, 90% interval 1.15 to 1.74. The synonymous counts are far from expectation, so gnomAD's model fits this gene poorly and the ratio says little. Missense variants: 958 observed, 756.54 expected, observed/expected ratio (o/e) 1.27, 90% interval 1.2 to 1.34. Synonymous variants: 424 observed, 326.1 expected, observed/expected ratio (o/e) 1.3, 90% interval 1.2 to 1.41.
Gene-disease validity (ClinGen):
ClinGen rates the evidence that CDT1 causes each of these diseases.
Meier-Gorlin syndrome 4 (autosomal recessive): Definitive.
Homologues: Orthologues: chimpanzee CDT1 (99% identical), macaque CDT1 (93% identical), pig CDT1 (75% identical), mouse Cdt1 (73% identical), dog CDT1 (73% identical), guinea pig CDT1 (72% identical), rat Cdt1 (72% identical), rabbit CDT1 (54% identical), tropical clawed frog cdt1 (53% identical), zebrafish cdt1 (49% identical), Drosophila melanogaster dup (32% identical), Caenorhabditis elegans cdt-1 (22% identical).
Diseases named in the same sentence as CDT1 in open-access papers:
CDT1 is named in the same sentence as 65 diseases in open-access papers, as found by Europe PMC text mining. Sharing a sentence is not in itself a finding about the gene and the disease. The quoted sentences say what the papers report.
breast carcinoma (12 papers, 2010 to 2024). "High levels of CDT1 and CDC6 are associated with poorer survival in the breast cancer patients, suggesting that CDT1 and CDC6 are potential therapeutic targets for treatment of breast cancer." (PMID 36359297, 2022). "Further, high CDT1 expression has been associated with undesirable prognosis of breast cancer patients." (PMID 34631549, 2021). "In the present report, we found that expression of Cdc6 and Cdt1 was positively correlated with MCM2-7 overexpression, while high levels expression of Cdc6 and Cdt1 were associated with poor prognosis in breast cancer patients." (PMID 28428557, 2017). "Both Cdc6 and Cdt1, when expressed in a high level, alone or in combination, were significantly associated with poorer survival in the breast cancer patient cohort (n = 1441)." (PMID 28428557, 2017). "Indeed, in the present study, we found that a high level expression of either Cdc6 or Cdt1 in the breast cancer specimens was associated with a shorter survival of the patients." (PMID 28428557, 2017). "In breast cancer and colon cancer, POLQ is associated with the upregulation of genome stability genes and replication initiation proteins such as CDC6, CDT1, and CDC45." (PMID 38270643, 2024). "Overexpression of CDT1 was revealed to be a predictor of low survival in hepatocellular carcinoma patients and a prognostic marker for breast cancer patients." (PMID 35412947, 2022). "CDT1 was highly expressed in various tumors including cervical cancer, breast cancer, colorectal cancer, and liver cancer." (PMID 34631549, 2021). "Elevated CDT1 expression has been detected in several cancers, including lung cancer, breast cancer, and lymphoma." (PMID 34631549, 2021). "We further tested the expression level of Cdc6 and Cdt1 in three breast cancer cell lines; three breast cell lines were chosen based on their aggressiveness and ER-positivity as well as their popularity in the literature." (PMID 28428557, 2017). "The prognostic value of CDT1 has been recently evaluated in breast cancer, whose over-expression was observed in tumor cells and significantly associated with poor patient survival." (PMID 28754978, 2017). "To confirm these in vitro findings, we investigated the impact of letrozole treatment on the expression levels of Cdc6 and Cdt1 in breast cancer." (PMID 28428557, 2017). "Different mechanism of action for MLN4924 radiosensitization (p21 in breast cancer cells vs. CDT1 and WEE1 in pancreatic cancer cells) reflected a cell-line dependent response to inactivation of SCF E3 ligases." (PMID 22457814, 2012). "CDT1 was upregulated in both hepatocellular carcinoma and breast cancer." (PMID 35412947, 2022). "Additionally, a recent study reported that the transcriptional level of CDT1 was significantly increased in breast cancer cells compared with normal breast epithelial cells." (PMID 34631549, 2021). "Here, we investigated whether Cdc6, Cdt1 or Orc1 also confer prognostic value to breast cancer patients." (PMID 28428557, 2017). "And some of them, such as Cdc6 and Cdt1, are elevated by E2 treatment in breast cancer." (PMID 21040551, 2010). "The top three genes (WDR62, CDT1 and MCM2) positively correlated with POLD1 expression play important roles in cell proliferation and apoptosis, and their upregulation has been proved to be associated with tumors development and worse prognosis, such as breast cancer and lung adenocarcinoma." (PMID 35189839, 2022). "However, the roles of Cdc6 and Cdt1, which work with MCMs to regulate DNA replication, in breast cancers are largely unknown." (PMID 28428557, 2017). "Since Cdc6, Cdt1 and Orc1 work cooperatively with MCM2-7 to initiate DNA replication, we have investigated whether there are associations between the numbers of overexpressed MCM2-7 genes and expression of these three genes in breast cancer specimens." (PMID 28428557, 2017). "However, little is known regarding the prognostic significance of Cdc6 and Cdt1 in breast cancer." (PMID 28428557, 2017).
breast carcinoma (continued). "Since Cdc6, Cdt1 and Orc1 work cooperatively with MCM2-7 to initiate DNA replication, in our current study we have investigated whether there are associations between these three genes and clinicopathological parameters or expression of MCMs in breast cancer." (PMID 28428557, 2017). "We went on to investigate the impact of inhibited ER signalling on the expression of Cdc6 and Cdt1 in the ER-positive MCF7 breast cancer cells and human breast cancer specimens." (PMID 28428557, 2017). "Unlike the mechanism by which MLN4924 sensitized pancreatic cancer cells to radiation via causing accumulation of CDT1 and WEE1 to trigger DNA damage response/aneuploidy and G2/M arrest, respectively, MLN4924-induced radiosensitization in breast cancer cells appeared not to involve CDT1 or WEE1." (PMID 22457814, 2012). "However, since Cdc6, Cdt1 and Orc1 all play an important role in DNA replication licensing, the reasons for Orc1 mRNA expression not being a prognostic factor in breast cancer may be worth further investigation." (PMID 28428557, 2017).
lung carcinoma (10 papers, 2013 to 2025). "Further studies are necessary to clarify the involvement of DDB1 and CDT1 in lung cancer progression, as well as their role in the regulation of circ_0004470 associated with lung cancer progression." (PMID 40157540, 2025). "Kaplan–Meier analysis from a public database indicated that high CDT1 expression is associated with lower overall survival in lung cancer patients." (PMID 40157540, 2025). "Analysis of lung cancer clinical samples showed that the expression of DDB1 was significantly lower in lung cancer tissues than in normal tissues, whereas CDT1 was expressed at high levels in lung cancer tissues (left)." (PMID 40157540, 2025). "CDT1 was upregulated in the vast majority of cancer tissues, based on pan-cancer analysis in TCGA and GEO datasets, as to lung cancer, the level of CDT1 expression was much higher in LUAD tissue than in healthy lung tissue." (PMID 37790630, 2023). "Collectively, overexpressed SIRT3 elevates expression of FOXO3a/CDT1 axis, thus, contributing to enhanced sensitivity of lung cancer cells." (PMID 33655712, 2021). "The expression patterns of SIRT3, FOXO3, and CDT1 were determined using RT‐qPCR and Immunoblotting in lung cancer." (PMID 33655712, 2021). "Mechanically, overexpressed SIRT3 elevates expression of FOXO3a/CDT1 axis, thus, contributing to enhanced cell apoptosis and sensitivity of lung cancer cells to cisplatin." (PMID 33655712, 2021). "Existing studies were consistent with our findings supporting that CDT1 was repressed in lung cancer tissues and cells, and its elevation fundamentally contributed to inhibited cisplatin resistance of lung cancer cells." (PMID 33655712, 2021). "Coherently, FOXO3 promoted cisplatin resistance to lung cancer cells, which was reversed by CDT1 elevation." (PMID 33655712, 2021). "The expression of CDT1 was deregulated by administration of hexavalent chromium (a well‐known carcinogen) treatment in lung cancer." (PMID 33655712, 2021). "In subsequent experiments, we found that FOXO3 positively regulated CDT1 expression, and its elevation inhibited cell cisplatin resistance of lung cancer cells as well as inhibited viability, proliferation." (PMID 33655712, 2021). "The elevation of SIRT3, FOXO3, or CDT1 inhibited cell cisplatin resistance of lung cancer cells as well as inhibited viability, proliferation, and invasion in vitro." (PMID 33655712, 2021). "Taken together, SIRT3 regulates FOXO3/CDT1 axis, thus enhancing cisplatin resistance of lung cancer cells." (PMID 33655712, 2021). "Taken together, SIRT3 elevation inhibits cisplatin resistance of lung cancer cells through FOXO3/CDT1 axis in vivo." (PMID 33655712, 2021). "Furthermore, under hypoxia, a factor that induces glycolysis, CCNA2 expression was upregulated in acute myeloid leukemia, and a similar relationship between hypoxia and CDT1 was found in lung cancer as well." (PMID 38794139, 2024). "However, in a study of lung cancer, CDT1 expression was shown to be suppressed in cancer tissues and cells." (PMID 35412947, 2022). "The role of SIRT3/FOXO3a/CDT1 axis in cisplatin resistance of lung cancer." (PMID 33655712, 2021). "SIRT3, FOXO3, and CDT1 expression was suppressed in the lung cancer tissues and cells." (PMID 33655712, 2021). "As expected, Myc‐CDT1 were interacted with Flag‐FOXO3 in lung cancer cells." (PMID 33655712, 2021). "In subsequent analysis, to elucidate whether FOXO3/CDT1 axis was related to resistance of cisplatin to lung cancer, FOX3 was downregulated and upregulated in A549 cells, and then, treated with cisplatin." (PMID 33655712, 2021).
lung carcinoma (continued). "Poorly expressed CDT1 has been reported to be evident following Cul4A overexpression‐induced transgenic mouse model of lung tumorigenesis, and Cul4A depletion contributed to increased sensitivity to chemotherapy drug cisplatin by elevating CDT1 expression in lung cancer cells." (PMID 33655712, 2021). "Our findings support the hypothesis that overexpression of SIRT3 elevates FOXO3a/CDT1 axis, thus contributing to inhibited lung cancer cell viability, proliferation, and invasion as well as enhanced cell apoptosis and sensitivity of lung cancer cells to cisplatin." (PMID 33655712, 2021). "However, upstream targets of CDT1 in lung cancer remains unidentified." (PMID 33655712, 2021). "Chromatin licensing and DNA replication factor 1 (CDT1), a cell cycle–regulated partner of DDB1, is upregulated in several early precancerous lesions in lung cancer." (PMID 40157540, 2025). "In NNK- and Cd-transformed cells and lung cancer cell lines (A549, H1299, and H446), DDB1 was downregulated and CDT1 was upregulated, consistent with the results in clinical samples." (PMID 40157540, 2025).
Meier-Gorlin syndrome (8 papers, 2012 to 2024). "In line with this, a study found that the CDT1 gene variants were related to Meier-Gorlin Syndrome patients with microtia phenotypes." (PMID 38594752, 2024). "A form of dwarfism known as Meier-Gorlin syndrome (MGS) is caused by recessive mutations in one of six different genes (ORC1, ORC4, ORC6, CDC6, CDT1, and MCM5)." (PMID 29036220, 2017). "Recently, mutations in genes encoding ORC1, ORC4, ORC6, CDT1, and CDC6 were identified in patients displaying Seckel syndrome (SS) and/or Meier-Gorlin syndrome (MGS)." (PMID 23516378, 2013). "Mutations in ORC1, ORC4, ORC6, CDT1, and CDC6, which encode proteins required for DNA replication origin licensing, cause Meier-Gorlin syndrome (MGS), a disorder conferring microcephaly, primordial dwarfism, underdeveloped ears, and skeletal abnormalities." (PMID 23516378, 2013). "Additionally, mutations in key components involved in initiation of DNA replication, such as ORC1, ORC4, ORC6, CDT1, CDT6, and CDC45, have been reported to be the cause of Meier-Gorlin syndrome, a primordial dwarfism syndrome." (PMID 28915237, 2017). "Meier-Gorlin syndrome (MGS) is caused by mutations in components of the prereplication and pre-initiation DNA replication complexes (ORC1, ORC4, ORC6, CDT1, CDC6, GMNN, CDC45), which license replication origins and mediate loading and functioning of the replication fork helicase." (PMID 28630177, 2017).
cervical carcinoma (6 papers, 2012 to 2023). A carcinoma arising from either the exocervical squamous epithelium or the endocervical glandular epithelium. "An existing study documented rapid proteolysis of CDT1 was induced by cisplatin treatment in human cervical carcinoma HeLa and hepatocarcinoma HepG2 cells." (PMID 33655712, 2021). "Here, we show that Cdt1 is targeted for proteolysis-dependent degradation in response to cisplatin, in both the cervical carcinoma cell line HeLa and the hepatoma cell line HepG2, suggesting that this drug is able to activate the Cdt1-dependent checkpoint in different cancer cells." (PMID 22479651, 2012).
prostate carcinoma (6 papers, 2013 to 2025). A carcinoma that arises from epithelial cells of the prostate gland. "There are other pre-RC components, such as Orc2, Cdt1, and Mcm7, that are also reported to be associated with AR in prostate cancer cells." (PMID 23437213, 2013). "In our study, MLN4924 caused accumulation of WEE1/p21/p27, CDT1/ORC1 and NOXA/BIK, which were associated with MLN4924-IR-enhanced G2 cell-cycle arrest, DNA damage and apoptosis in prostate cancer cells." (PMID 27224919, 2016). "Thus, in the meta-analyses of prostate cancer, we explored two top gene sets whose GSAS were driven by ESM1, and by SMC6, CDT1 and RAD18." (PMID 38597610, 2024).
hepatocellular carcinoma (5 papers, 2021 to 2022). A malignant tumor that arises from hepatocytes. "CDT1 was proposed as a potential biomarker in hepatocellular carcinoma through the analysis of gene expression profiles, and its role was validated in vitro." (PMID 36338962, 2022). "The expression of Cdt1 is frequently elevated in aggressive human hepatocellular carcinomas and in various breast and gastric carcinomas, suggesting aberrantly elevated levels of Cdt1 may contribute to these malignancies." (PMID 34068957, 2021).
ovarian carcinoma (5 papers, 2020 to 2024). A malignant neoplasm originating from the surface ovarian epithelium. "Although LIMCH1, CRLS1, CDT1, CNIH4 have been associated with various cancers, their relationship with ovarian cancer has been proposed in this study for the first time to the best of our knowledge." (PMID 36338962, 2022). "CDT1 might be a novel target in ovarian cancer due to its relationship with other cancers, and with the proteins that were reported to be involved in the progression of the disease." (PMID 36338962, 2022). "As a result, six genes (CDT1, CNIH4, CRLS1, LIMCH1, POC1A, and SNX13), and two miRNAs (mir-147a, and mir-103a-3p) were suggested as novel candidate prognostic biomarkers for ovarian cancer." (PMID 36338962, 2022). "In ovarian cancer, depleting CUL4A mimics MLN4924-induced death, and depleting the replication origin licensing factor CDT1, a CUL4A target, rescues these effects." (PMID 32123578, 2020). "Furthermore, LIMCH1, CRLS1, CDT1, and CNIH4 were found to be associated with various cancer types, but their roles in ovarian cancer have not been identified yet." (PMID 36338962, 2022).
liver cancer (4 papers, 2011 to 2025). An epithelial or non-epithelial malignant neoplasm that arises from the liver. "The Cul4A gene is amplified in human breast and liver cancers, and loss-of-function of Cul4 results in the accumulation of the replication licensing factor CDT1 in Caenorhabditis elegans embryos and ultraviolet (UV)-irradiated human cells." (PMID 21989042, 2011). "CDT1 is a key regulator in the cell cycle and DNA replication, and has been shown to promote the occurrence and development of liver cancer." (PMID 40255404, 2025). "Our study findings demonstrate the potential diagnostic and prognostic significance of CDT1 expression in HCC, and elucidate the potential molecular mechanism underlying its role in promoting the occurrence and development of liver cancer." (PMID 34631549, 2021). "Further, analysis of CDT1 expression levels in multiple common cancer cell lines from the CCLE database indicated that liver cancer cells had relatively higher CDT1 expression than other tumor cells." (PMID 34631549, 2021). "Based on the results of single-cell pseudotime analysis, we examined the changes in the expression levels of the shared pathogenic genes (IGSF3, CENPW, CDC6, CDT1) from adjacent non-tumor cells to liver cancer cells during the continuous process." (PMID 40433415, 2025).
colon cancer (3 papers, 2020 to 2024). "Consistent with that result, Cullins redundantly ubiquitylate the replication licensing factor CDT1, and co-knockdown of CUL1/4A/4B is necessary to mirror MLN4924-induced endoreplication in HCT-116 colon cancer cells." (PMID 32123578, 2020).